ACLY (ATP citrate lyase)
Diseases named in the same sentence as ACLY in open-access papers (continued):
Sharing a sentence is not in itself a finding about the gene and the disease.
cancer (311 papers, 2009 to 2026). A tumor composed of atypical neoplastic, often pleomorphic cells that invade other tissues. "In many cancer types, including glioblastoma, colorectal cancer, breast cancer, non-small-cell lung cancer, and hepatocellular carcinoma, high levels of ACLY expression are associated with progression." (PMID 40002387, 2025). "Expression or activity of ACLY is associated with tumor progression in glioblastoma, colorectal, breast, lung, and hepatocellular carcinomas and promotes cancer cell proliferation and stemness." (PMID 41306968, 2025). "Pharmacological inhibition of SLC25A1 and ACLY significantly enhances cancer cell susceptibility to ferroptosis both in vitro and in vivo." (PMID 39881208, 2025). "The data described in the present study showed that the combined inhibition UBE2C and PLK1 or BIRC5 caused a decrease in the mRNA expression of ACLY, suggesting a possible novel strategy for cancer therapy." (PMID 37958642, 2023). "Conversely, pharmacological ACLY inhibition impedes aberrant AP-1 signaling in PD-1-deficient T-NHLs and is toxic to these cancers." (PMID 37723306, 2023). "Upregulation of ACLY gene, which plays an important role in synthesis of fatty acids in cancer proliferation, is associated with BC and its recurrence." (PMID 36936429, 2023). "ACLY has been associated with cancer and studies have demonstrated that some types of tumor cells can be suppressed by its inhibition." (PMID 36765905, 2023). "The survival analyses revealed that the high expression of the ACLY was significantly associated with a poor prognosis in patients with seven cancers." (PMID 37958642, 2023). "ACLY overexpression has been associated with increased tumor progression in many cancers: breast, lung, brain, colorectal, hepatocellular, and others." (PMID 35178152, 2022). "While Gln deprivation was somewhat toxic to KRas-driven cancer cells by itself, addition of the ACLY inhibitor SB-204990 increased the loss of cell viability." (PMID 36269753, 2022). "ACLY overexpression has been associated with increased tumor progression in many cancers, including breast, lung, brain, colorectal, hepatocellular, and others." (PMID 35205619, 2022). "Recently, independently inherited variants in ACLY were investigated to determine their impacts on lipid and lipoprotein levels as well as cancer and cardiovascular events in a large cohort of ∼650,000 participants." (PMID 35402505, 2022). "CUR has regulatory effects on various enzymes associated with inflammation and cancer, including fatty acid synthase, ATP-citrate lyase (ACLY), stearoyl-CoA desaturase 1, and cholesterol O-acyl-transferase." (PMID 35056675, 2022). "In exploring a potential functional interaction of SIRT6 with ACLY, we were surprised to observe that ACLY protein levels were consistently elevated in SIRT6-deficient cancer cells." (PMID 34573442, 2021). "Consistent with our findings, the up-regulation of ACLY levels have been implicated in promoting cancer malignancy and poor prognosis." (PMID 34573442, 2021). "The deregulation of ACLY is linked to various diseases including cancers, due to its central role in nutrient metabolism and biosynthesis." (PMID 34573442, 2021). "In this study, we chose four different types of cancer that are tightly associated with human life and health, and demonstrated that ACLY acted as a common target of miR-22 despite of the tumor types." (PMID 27317765, 2016). "Constitutive PI3K-AKT pathway activation in cancer cells is associated with elevated ACLY-dependent acetyl-CoA production and histone acetylation." (PMID 27248322, 2016). "Increased abundance of ACLY and pACLY was also associated with proliferation in other types of aggressive cancers." (PMID 25277207, 2014). "The up-regulation of ACLY in cancer cells is associated with poor prognosis in patients with HNSCC." (PMID 40821122, 2025).
cancer (continued). "The upregulation of enzymes like ACLY is responsible for this metabolic change, which not only supplies essential lipids for the formation of cell membranes but also enhances cancer-causing signaling pathways involved in cell survival, growth, and specialization." (PMID 39148124, 2024). "While the two ACLY splice isoforms are expressed broadly across tissues, are regulated in tumors and associated with cancer phenotypes, and include sites that may be modified post-translationally, the functions of exon 14 remain elusive." (PMID 38815867, 2024). "We next tested whether ACLY loss rendered these cancer cells reliant on acetate for proliferation and acetyl-CoA synthesis." (PMID 37134161, 2023). "We therefore examined whether we could rescue the loss of cell viability caused by Gln deprivation or utilization and ACLY inhibition in KRas-driven cancer cells with α-KG." (PMID 36269753, 2022). "ATP citrate lyase, encoded by Acly, is an important enzyme in controlling substrate supply for lipid synthesis de novo and is upregulated to different degrees in many kinds of cancers." (PMID 35205403, 2022). "Upregulation of ATP citrate lyase promotes cancer cell proliferation and colony formation, and increased monoacylglycerol lipase could increase cancer risk." (PMID 36072980, 2022). "Interestingly, tumor progression is associated with an increase in lipid synthesis, and thus ACLY tends to be overexpressed in such cancer cells to accelerate lipid synthesis and tumor progression." (PMID 34048454, 2021). "Little is known to the association of ACLY gene with cancer prognosis." (PMID 25890184, 2015). "Some studies have also demonstrated that ACLY is also a cancer gene associated with metabolism." (PMID 26501265, 2015). "Several cancer cell lines, particularly under conditions of ACLY deficiency, hypoxia or nutrient limitation, favor this pathway, but even under glucose-replete conditions ACSS2 may be preferably used to support de novo lipogenesis, as in case of human cytomegalovirus infection (HMCV)." (PMID 33679780, 2021). "The relatively high drug concentrations required to completely inhibit ACLY activity and differences in ACLY activity dependency for glycolysis-fueled lipogenesis rates currently limit cancer therapeutics targeting ACLY." (PMID 40814339, 2025). "Based on this, another approach in cancer therapy is to combine ACLY inhibitors with AMPK activators." (PMID 41421797, 2025). "The overexpression of critical enzymes, such as FASN and ACLY, enables cancer cells to enhance de novo fatty acid synthesis, thereby driving their proliferation and survival." (PMID 41009695, 2025). "Higher FPKM values for FADS1, ELOVL5, and ACLY were detected in cancer tissues than in adjacent normal tissues (P < 0.01; P < 0.01; P < 0.01), suggesting that alterations in lipid metabolism in ESCC are mediated by altered expression of these genes." (PMID 41184824, 2025). "In human cancers, reduced ACLY expression correlates with cGAS-STING activation and decreased T-cell infiltration." (PMID 41306968, 2025). "To date, ACLY has been acknowledged as an OXPHOS activator in skeletal muscles or cancer cells by diverse mechanisms." (PMID 39835169, 2025). "ATP citrate lyase (ACLY) is a key enzyme involved in the metabolic reprogramming of cancer cells, as it catalyzes the conversion of citrate to acetyl-CoA, a precursor for lipid synthesis." (PMID 41330897, 2025). "The known interactions between ACLY/AMPK and ACLY/ACC signaling in cancer cells highlight the metabolic shifts induced by methionine restriction." (PMID 40427696, 2025). "The significantly upregulated expression of ACLY in epithelial cells from primary cancer and CRPC samples suggests increased utilization of citric acid in the lipid synthesis pathway during tumorigenesis." (PMID 39988626, 2025).
cancer (continued). "In nasopharyngeal carcinoma, lncRNA TINCR promotes cancer cell proliferation, metastasis, and chemotherapy resistance by inhibiting ACLY ubiquitination degradation and regulating acetyl-CoA metabolism." (PMID 40821122, 2025). "In cancer, dysregulated Akt can directly phosphorylate and activate ATP-citrate lyase (ACLY), leading to increased synthesis of acetyl-CoA." (PMID 41421797, 2025). "SLC25A1 and ACLY support rapid cell proliferation and epithelial-mesenchymal transition and maintain cancer stem cell stemness by upregulating fatty acid synthesis and histone acetylation." (PMID 39881208, 2025). "ACLY is often upregulated in various cancers, and its inhibition has emerged as a potential target for cancer therapy." (PMID 41330897, 2025). "Unlike normal cells, which primarily obtain fatty acids (FAs) from dietary sources, cancer cells enhance de novo fatty acid synthesis by modulating ACLY, ACC, FASN and SCD." (PMID 41154605, 2025). "This ACLY-dependent cycle is prominent in proliferating cells such as cancer, wherein ACLY depletes cytosolic citrate and NADH, activates glycolysis, and provides cytosolic acetyl-CoA for protein acetylation and membrane synthesis." (PMID 40499285, 2025). "We found that ACLY knockdown heightened cell susceptibility to RSL3- and erastin-induced ferroptosis across various cancer cell lines, including A375, A549, RKO, and SK-MEL-30." (PMID 39881208, 2025). "One of the pioneering studies highlighting the significance of lipid metabolism in cancer showed that ACLY activity was 160 times higher in breast cancer tumors compared with normal tissue." (PMID 40723225, 2025). "While therapeutic strategies such as FASN inhibition or ACLY/SCD1 synthetic lethality have shown promise in other cancers, the lipid metabolic dependencies specific to CCA remain largely unexplored." (PMID 41291880, 2025). "Since ACLY is typically overexpressed in a range of cancers, one cancer treatment option is to alter the enzyme's citric acid binding site through indirect transcyclic citric acid‐binding." (PMID 40956032, 2025). "Cancer cells exhibit a heightened reliance on de novo lipogenesis, even in the presence of abundant extracellular lipids, with key enzymes such as ACLY, ACC1, and FASN identified as promising therapeutic targets." (PMID 41291880, 2025). "We detected in PR elevated levels of enzymes (COX-2, ACSS2, FDPS, FASN, ACAT2, ACLY, SLC12A2) and metabolites (arachidonic acid and carnitine) involved in lipid metabolism, which have been linked to radioresistance of cancer cells." (PMID 38410100, 2024). "Accumulating evidence has shown that multiple lipogenic enzymes, such as FASN, ACC, SCD1, and ACLY, are aberrantly upregulated in a wide variety of cancers, driving FA synthesis and contributing to lipogenesis and the progression of cancer cells." (PMID 38491348, 2024). "Key enzymes in fatty acid synthesis, such as Fatty Acid Synthase (FASN), Acetyl-CoA Carboxylase (ACC), and ATP Citrate Lyase (ACLY), are upregulated in various cancers and are closely associated with tumor progression." (PMID 39744129, 2024). "Cancer cells exhibit increased de novo adipogenesis due to elevated expression of lipogenic enzymes like ATP citrate lyase (ACLY) and fatty acid synthase (FASN)." (PMID 38782774, 2024). "Despite these intriguing patterns of ACLY splicing in healthy and cancer tissues, functional differences between the isoforms remain elusive." (PMID 38815867, 2024). "Cancer cells can upregulate acetyl-CoA synthetase 2 (ACSS2) expression to generate acetyl-CoA from acetate or upregulate ATP-citrate lyase (ACLY) expression to convert citrate to acetyl-CoA." (PMID 39090116, 2024). "In this study, we report the expression of long and short ACLY splice isoforms in mammalian tissues, along with evidence that exon 14 inclusion is increased in multiple cancer types." (PMID 38815867, 2024).
cancer (continued). "Cancer cells activate lipogenic enzymes, including ATP-citrate lyase (ACLY), acetyl-CoA carboxylase (ACC), CoA carboxylase (ACACA), fatty acid synthase (FASN), and SCD, resulting in increased production of fatty acids." (PMID 38765144, 2024). "In the context of cancer immunotherapy, ACLY inhibition has been reported to overcome immunotherapy resistance through polyunsaturated fatty acid peroxidation and activation of the cGAS-STING pathway." (PMID 39399493, 2024). "ACLY has been investigated as a potential therapeutic target for metabolic diseases and cancer, and several ACLY inhibitors have been developed." (PMID 38815867, 2024). "The expression of various lipid synthases is elevated in cancer cells, including sterol regulatory element binding proteins (SREBPs), ATP-citrate lyase (ACLY), acetyl-CoA carboxylase (ACC), fatty acid synthase (FASN), and stearoyl-CoA desaturase 1 (SCD1)." (PMID 38994204, 2024). "In cancer cells, the expression of ACLY is often upregulated, and it plays a significant role in the occurrence, development, and metastasis of tumors." (PMID 39744129, 2024). "ACLy has been found to be upregulated in resistant CRC cells and, in general, in the glycolytic phenotype of tumors; thus, ACLy has become a novel target for cancer therapeutics." (PMID 38731601, 2024). "Aberrant expression of ACLY has been demonstrated in several tumors and is correlated with malignant tumor progression." (PMID 39399493, 2024). "The ATP citrate lyase (ACLY) inhibitor SB-204990, in combination with glutamine deprivation, causes KRAS-driven cancer cell death." (PMID 39609317, 2024). "The knockdown of ACLY in PSCs led to a significant reduction in the survival of cancer cells under low pH upon CM transplantation." (PMID 38429478, 2024). "The observed differences in palmitate isotopologue pattern, increase in M + 0 and shift toward isotopologues with lower mass were remarkably similar to those observed after exposure of cancer cells to experimental hypoxia or silencing of ACLY." (PMID 39251875, 2024). "The inhibition of ACLY can be bypassed in some cancer cells and in the livers of mice fed a high-fructose diet through the upregulation of ACSS2." (PMID 37958642, 2023). "The elevation of lipogenic enzymes, including ATP-citrate lyase (ACLY) and acetyl-CoA synthetase 2 (ACSS2), resulted in increased fatty acid synthesis and is often associated with poorer prognosis in cancer patients." (PMID 36677015, 2023). "ACLY has been shown to be highly expressed in a variety of cancers, and its inhibitor has a more significant anticancer effect in high-glycolytic cells." (PMID 37056351, 2023). "ACLY is a key enzyme that catalyzes the starting point for fatty acid synthesis, and it is a potential target for anti-cancer drugs because previous studies have shown that ACLY inhibition dramatically inhibits cell proliferation." (PMID 37899460, 2023). "ACLY phosphorylation activated by Akt promotes histone acetylation in both cancer and immune cells present in TME, inducing their proliferation." (PMID 38060103, 2023). "Further studies have found that ACLY inhibitors inhibit tumor growth, further supporting the role of ACLY in promoting cancer 33-35." (PMID 37497413, 2023). "Our present study first examined the effects of the pharmacological combined inhibition of PLK1 and ACLY on the cell proliferation and clone formation of several cancer cell types." (PMID 37958642, 2023). "Supporting this, the ATP citrate lyase (ACLY), an enzyme that transforms citrate into acetyl-CoA, is necessary for cancer cells to multiply at optimum rates, while normal cells cannot do so because of a metabolic transition from glucose to acetate." (PMID 36831413, 2023). "ATP-citrate lyase (ACLY) inhibitors are emerging as potential therapeutics for metabolic diseases and cancer, targeting key enzymes involved in de novo lipogenesis." (PMID 37371893, 2023).
cancer (continued). "ACLY is highly expressed or activated in several cancers, supporting tumor cell growth through lipogenesis." (PMID 38060103, 2023). "The pharmacological or genetic suppression of ACLY dramatically decreases cancer cell growth and promotes apoptosis." (PMID 36983670, 2023). "Our study reveals the potential mechanisms through which cell-cycle-related genes regulate metabolism and proposes a potential combined targeted therapy for patients with higher PLK1 and ACLY expression in pan-cancer." (PMID 37958642, 2023). "ACLY is up-regulated in various tumors and plays a crucial role in cancer cell proliferation, growth, migration and apoptosis." (PMID 38189049, 2023). "Increased levels of FASN and ACLY contribute to cancer stem cell-like properties, self-renewal induction, cellular steatosis, affecting HCC progression." (PMID 38189049, 2023). "The upregulation of ACC1/2, ACSS, and ACLY has been observed in many cancer types Interestingly, ACLY is also involved in nuclear dynamics by providing acetyl CoA for histone acetylation after their nuclear translocation." (PMID 37256177, 2023). "In the cytoplasm, MORC2 interacts with adenosine triphosphate (ATP)-citrate lyase (ACLY) to promote lipogenesis and cholesterogenesis in cancer." (PMID 37892209, 2023). "In many cancer systems, de novo lipogenesis proteins ATP-citrate lyase (ACLY), acetyl-CoA carboxylase 1 (ACC1), and fatty acid synthase (FASN) have been reported to be upregulated." (PMID 38069382, 2023). "ACLY depletion in various cancer cell lines exerts an anti-proliferative effect through the generation of mitochondrial ROS and AMPK activation accompanied by triglyceride accumulation and down-regulation of carnitine palmitoyltransferase 1A." (PMID 38060103, 2023). "Inhibition of ACLY by RNA interference or chemical inhibitor SB-204990 inhibited cancer proliferation." (PMID 35646898, 2022). "Recent studies revealed that the elevation of ACLY expression and activity promotes cancer cell growth and metastasis, and phosphorylation of ACLY contributes to cellular acetyl-CoA production and then increases histone acetylation." (PMID 35027547, 2022). "Another factor that supports cancer progression through cholesterol synthesis is ATP citrate lyase (ACLY) enzyme, which converts citrate to acetyl-CoA." (PMID 36479100, 2022). "The depletion of ATP citrate lyase suppressed tumor growth, so it has been identified as a potential molecular target for cancer therapy." (PMID 35205403, 2022). "In the work presented here, we provide evidence that the increase in mTORC2 (Akt phosphorylation at S473) in response to exogenously supplied OA and de novo synthesis of PA lead to the phosphorylation of ACLY in KRas-driven cancer cells." (PMID 36269753, 2022). "We examined the impact of glutamine (Gln) deprivation in combination with inhibition of ACLY on the viability of KRas-driven cancer cells." (PMID 36269753, 2022). "Among the phosphoproteins, we validated four enzymes associated with cancer and present only in sEVs isolated from MCF7 and MDA-MB-231 cell lines: ATP citrate lyase (ACLY), phosphofructokinase-M (PFKM), sirtuin-1 (SIRT1), and sirtuin-6 (SIRT6)." (PMID 35203617, 2022). "ACLY plays a role in modulating proliferation, growth, migration, and apoptosis that has been reported in many cancer cells." (PMID 35203617, 2022). "High levels of ACLY have been detected in various cancers such as breast, bladder, colorectal, lung, liver, prostate, and stomach tumors." (PMID 35056675, 2022). "ATP citrate lyase (ACL) is an important enzyme that cleaves citrate to generate oxaloacetate and Acetyl-CoA in various cancers such as BC." (PMID 36230935, 2022). "ACLY activation is promoted by increased levels of glucose and insulin-like growth factors, which subsequently intervene in cancer progression." (PMID 35056675, 2022). "ACLY plays a profound regulatory role in different cancers, and the dysregulation of ACLY expression is more likely to make cells cancerous." (PMID 39086974, 2022).